NT5DC1 (5'-nucleotidase domain containing 1)
Synonyms: NT5C2L1; LP2642; dJ486I3.1; MGC24302; C6orf200
Tractability: PROTAC: ubiquitination databases record sites on it; its protein half-life has been measured.
Target class: Enzyme; Hydrolase
Gene: Protein-coding gene on chromosome 6 (116,100,837 to 116,249,497, forward strand). Ensembl gene ENSG00000178425.
Subcellular location (Human Protein Atlas): Nucleoplasm; Cytosol
Gene Ontology:
Molecular function: protein binding; phosphatase activity
Genetic constraint (gnomAD): Loss-of-function variants: 5 observed, 7.41 expected, observed/expected ratio (o/e) 0.68, 90% interval 0.35 to 1.41. That is too few expected variants to judge how well the gene tolerates losing a copy. Missense variants: 100 observed, 110.18 expected, observed/expected ratio (o/e) 0.91, 90% interval 0.77 to 1.07. Synonymous variants: 55 observed, 45.37 expected, observed/expected ratio (o/e) 1.21, 90% interval 0.98 to 1.52.
Homologues: Orthologues: chimpanzee NT5DC1 (99% identical), macaque NT5DC1 (92% identical), pig NT5DC1 (91% identical), dog NT5DC1 (90% identical), rabbit NT5DC1 (88% identical), guinea pig NT5DC1 (82% identical), rat Nt5dc1 (79% identical), mouse Nt5dc1 (79% identical), tropical clawed frog nt5dc1 (64% identical), zebrafish nt5dc1 (62% identical), Drosophila melanogaster Nt5a (31% identical). Paralogues in human: NT5DC3 (24% identical), NT5C2 (23% identical), NT5DC2 (22% identical), NT5DC4 (19% identical).
Diseases named in the same sentence as NT5DC1 in open-access papers:
NT5DC1 is named in the same sentence as 16 diseases in open-access papers, as found by Europe PMC text mining. Sharing a sentence is not in itself a finding about the gene and the disease. The quoted sentences say what the papers report.
breast carcinoma (1 paper, 2023). "The low expression level of NT5DC1 (P = 7.3e–06) and high expression level of NT5DC2 (P = 1.5e–06) indicated significantly shorter OS in breast cancer patients." (PMID 36820551, 2023). "The results of the TIMER database showed that the expression of NT5C2, NT5DC1, and NT5DC3 were significantly downregulated in breast cancer tissues, while the expression of NT5DC2 were upregulated." (PMID 36820551, 2023). "According to our study, the expression of NT5C2, NT5DC1, and NT5DC3 was downregulated, while the expression of NT5DC2 was upregulated in breast cancer tissues." (PMID 36820551, 2023). "There was a downregulation of NT5C2, NT5DC1, and NT5DC3 in breast cancer compared to normal tissues, and NT5DC2 instead." (PMID 36820551, 2023).
dementia (1 paper, 2024). Loss of intellectual abilities interfering with an individual's social and occupational functions.
cancer (3 papers, 2017 to 2023). A tumor composed of atypical neoplastic, often pleomorphic cells that invade other tissues. "NT5DC1 expression correlated with patient sex, NT5DC3 expression was significantly associated with cancer grade, and NT5DC4 expression was associated with tumor diameter." (PMID 37576396, 2023). "Likewise, we found a number of genes whose expression follows this pattern: late-stage cancers < early-stage cancers < normal tissue, such as ADHFE1, LOC653501, NT5DC1, RSBN1, SOCS2 and TAPT1 in five cancer types." (PMID 28427185, 2017).
adenocarcinoma (1 paper, 2020). A common cancer characterized by the presence of malignant glandular cells. "Other co-regulated genes of potential interest include TRIM27 (FDR-adjusted p = 0.025), as well as NT5DC1 (FDR-adjusted p = 0.003) and ARL6IP1 (FDR-adjusted p = 0.047), which were upregulated in the A549 adenocarcinoma alveolar basal epithelial cell line after exposure to IFN-α and IFN-γ for 6 h." (PMID 32413319, 2020).
NT5DC1 also shares sentences with these, for which no sentence is quoted: acute leukemia (1 paper); astrocytoma (1); chronic obstructive pulmonary disease (1); colorectal carcinoma (1); glioblastoma (1); hepatocellular carcinoma (1); laryngeal squamous cell carcinoma (1); leiomyosarcoma (1); lung carcinoma (1); membranous nephropathy (1); tumor (1); type 2 diabetes mellitus (1).